PI4KAP1 (phosphatidylinositol 4-kinase alpha pseudogene 1)
Gene: Transcribed unprocessed pseudogene on chromosome 22 (18,534,005 to 18,548,798, reverse strand). Ensembl gene ENSG00000274602.
Diseases named in the same sentence as PI4KAP1 in open-access papers:
PI4KAP1 is named in the same sentence as 2 diseases in open-access papers, as found by Europe PMC text mining. Sharing a sentence is not in itself a finding about the gene and the disease. The quoted sentences say what the papers report.
myositis (1 paper, 2018). "We found that PI4KAP1 had a higher expression in CD4+ T cells of HLA-DRB1*03-positive myositis and that TRGC2, CTSW, HPCAL4, ZNF683, and GOLGA8B had a higher expression in CD4+ T cells of HLA-DRB1*03-negative myositis patients." (PMID 30157932, 2018). "PI4KAP1 was found to have a higher expression in CD4+ T cells of HLA-DRB1*03-positive patients with myositis, and TRGC2, CTSW, HPCAL4, ZNF683, and GOLGA8B were found to have a higher expression in CD4+ T cells of HLA-DRB1*03-negative patients with myositis." (PMID 30157932, 2018).
PI4KAP1 also shares sentences with these, for which no sentence is quoted: Alzheimer disease (1 paper).